ZEB1 (zinc finger E-box binding homeobox 1)
Diseases named in the same sentence as ZEB1 in open-access papers (continued):
Sharing a sentence is not in itself a finding about the gene and the disease.
tumor (continued). "CDH1 transcriptional repressors, such as SNAI1 (SNAIL), SNAI2 (SLUG), ZEB1, ZEB2 (SIP1), E12/E47, and TWIST have traditionally been implicated in promoting EMT in various systems of embryonic development and tumor progression." (PMID 24968068, 2014). "Rip2-deficient tumors showed enhanced epithelial-to-mesenchymal transition, with elevated expression of zeb1, zeb2, twist, and snail in the tumor microenvironment." (PMID 24733360, 2014). "Multiple signaling pathways including TGFβ, Wnt and Notch working together with transcription factors such as Slug, Snail, Twist, Zeb1 and 2 suppress E-cadherin, induce EMT and result in loss of cell-cell adhesion, increased tumor progression and migration." (PMID 25216513, 2014). "It is known that EMT is a process associated with many factors, of which TGF-β, Vimentin, ZEB-1, SMAD-7, E-cadherin and N-cadherin molecules are closely associated with the typical phenotype change of EMT in the process of tumor cell growth." (PMID 24625224, 2014). "The miR-200 family plays a critical role in the suppression of epithelial-to-mesenchymal transition (EMT) and tumor cell migration, invasion, and metastasis by directly targeting ZEB1 (zinc finger E-box-binding homeobox 1) and ZEB2." (PMID 25295252, 2014). "We confirmed the key role of miR-150 as a tumor suppressor by directly and negatively targeting ZEB1 in EOC." (PMID 25090005, 2014). "Treatment of AsPC-1 xenografted mice with embelin induced the expression of E-cadherin and inhibited the expression of MMP-2, MMP-9, Snail, Slug, and Zeb-1 in tumor tissues compared to untreated control group." (PMID 24694877, 2014). "Members of the miR-200 family have been found to act as tumor suppressor miRNAs that inhibit EMT by down regulating the expression of ZEB1 and ZEB2." (PMID 24967704, 2014). "Once this process is under way in a tumor, it is typical to find a coordinated alteration in the expression of all these genes: the expression of ZEB1, ZEB2, VIM, and SNAI1 is upregulated, while the expression of CDH1 is downregulated." (PMID 25157365, 2014). "During tissue remodelling or tumor progression, several transcriptional repressors, such as Snail, Slug, ZEB1, ZEB2 and Twist1, can down-regulate E-cadherin expression leading to a reduction of cell-cell adhesion and promotion of EMT and cell motility." (PMID 24967704, 2014). "To characterize the function of the downregulation of ZEB1, we examined the expression of ZEB1, E-cadherin and Vimentin, respectively, in the tumor tissues of the EOC-bearing nude mice." (PMID 23842108, 2013). "The results showed a large decrease in E-cadherin staining and a reciprocal strong increase in the staining of ZEB1 and vimentin compared with control tumor (control and SMA-pirarubicin treated)." (PMID 24403226, 2013). "In these tumors, H3K27 acetylation level was higher in the tumor compartment than in the corresponding stroma where ZEB1 is more often expressed." (PMID 24216980, 2013). "Direct repression of MYB by the EMT driver ZEB1 builds onto the paradigm through which tumor growth, invasion, and metastasis are integrated." (PMID 24283570, 2013). "In order to better understand its effect on tumor function, ZEB-1 expression in HCC cells should be studied in isolation." (PMID 24304617, 2013). "We noticed that the enforced overexpression of miR200c in the CD44+CD117+CSCs significantly reduced the expressions of both ZEB1 and Vimentin, but increased the expression of E-cadherin in the RNA and the protein levels in tumor samples." (PMID 23842108, 2013). "As the ZEB1-positive population is characterised by high motility and increased chemoresistance, these cancer stem cells are a candidate population for tumour recurrence." (PMID 23818228, 2013). "Further, we observed that expression of MGMT, a major chemoresistance enzyme, increased towards the tumour edges in control tumours, and that ZEB1 and MGMT co-localise." (PMID 23818228, 2013).
tumor (continued). "As a result of the dysregulation, other proteins like MEIS1, MEIS2, TPM1, and ZEB1, which are putative tumor suppressors, are affected." (PMID 24391925, 2013). "To assess the effect of the down-regulation of ZEB1 on tumor metastasis, we performed H&E staining of lung tissue sections." (PMID 23842108, 2013). "MGMT was expressed independently of ZEB1 in these tumours, supporting c-MYB as intermediate regulator of MGMT." (PMID 23818228, 2013). "Immunofluorescent staining of patient tumour specimens revealed a 51 ± 9% overlap between ZEB1 and MGMT, which corroborated the significant correlation between ZEB1 and MGMT indicated by Western analysis (arrowheads)." (PMID 23818228, 2013). "The increased ZEB1 levels also ensure transcriptional inhibition of E-cadherin further stabilizing the mesenchymal morphology of the residual tumor." (PMID 24403226, 2013). "In contrast, ZEB1 was more often expressed in a restricted number of cells in the stroma of the tumor." (PMID 24216980, 2013). "EMT changes further increased the mesenchymal characteristics of this tumor as discerned by the decrease in E-cadherin and the increase in ZEB1 and vimentin." (PMID 24403226, 2013). "The presence of ZEB1-positive cells at the tumour invasion front strongly supports an invasive niche that contains cancer stem cells." (PMID 23818228, 2013). "Zeb1 and Zeb2 levels themselves are under control of miRs, including in EMT, which underlies the invasive properties of epithelial-derived tumor cells." (PMID 23531534, 2013). "Given that MMP2, MMP9, vimentin, and ZEB1 were regarded as potential elemental genes implying the pro-metastatic state and higher malignancy of tumor cells, as well as E2F1 downstream target genes, RT-PCR was performed to detect changes in mRNA levels." (PMID 24023875, 2013). "Staining for EMT markers revealed a decrease in E-cadherin especially in areas adjacent to necrotic regions and increase in ZEB1 and vimentin compared with control tumor (control and sunitinib treated)." (PMID 24403226, 2013). "Given the strong correlation with EGFR expression, it is conceivable that EGF signalling induces ZEB1 in these tumours." (PMID 23818228, 2013). "Further supporting the ability of TNFα + Estrogen + EGF stimulation to induce EMT was the prominent increase in the expression of the known EMT activators Zeb1, Snail, and Slug in the tumor cells (the EMT regulator twist was down-regulated; data not shown)." (PMID 24369447, 2013). "Forced expression of ZEB1 resulted in greater invasiveness of xenograft tumours, with tumour cells covering large distances along white matter tracts (arrowheads)." (PMID 23818228, 2013). "Univariate analysis with Cox proportional hazards model identified seven prognostic factors: histological type, tumor size, depth of invasion, lymph node invasion, lymphatic invasion, liver metastasis and ZEB1 expression." (PMID 23420790, 2013). "Staining of tissues collected 24 h after treatment displayed extensive decrease in E-cadherin and increase in ZEB1 and vimentin in surviving tumor adjacent to the thermal injury compared with control (control and thermal ablation treated)." (PMID 24403226, 2013). "Xenograft tumours of ZEB1 knockdown cells (shZEB1) were non-invasive, and consisted only of an expansive tumour mass." (PMID 23818228, 2013). "ZEB1 is expressed by infiltrating cells and some tumor cells and vimentin is also expressed at low levels (control)." (PMID 24403226, 2013). "The miR-200 family is largely known as tumor suppressive because of its inhibition of the epithelial-mesenchymal transition (EMT) through direct targeting of Zeb1 and Zeb2 TFs." (PMID 23144891, 2012). "Zinc-finger E-box binding homeobox 1 (ZEB1) is a candidate tumor suppressor gene since mRNA of ZEB1 was found to be down-regulated in ATL." (PMID 22943793, 2012).
tumor (continued). "The repression of these miRNAs coincides with publications showing that the down-regulation of miR-200 family contributes to metastasis of tumour cells by targeting ZEB1/ZEB2 and increasing E-cadherin." (PMID 22870299, 2012). "miR-200a and its orthologs, miR-200b, miR-200c, and miR-141 were first found tumor suppressors as they inhibit EMT through targeting Zeb1 and Zeb2." (PMID 23144891, 2012). "ZEB1 is a crucial inducer of epithelial-mesenchimal transition, which promotes malignant tumor progression, invasion, and metastasis of tumor cells in various human cancers." (PMID 23091478, 2012). "In contrast, the tumor stromal compartment showed nuclear zeb1 and twist expression in 75% and 52.4% of the cases, respectively." (PMID 21324165, 2011). "Our results indicate that positive selection of the tumor cells for estrogen and progesterone receptors is reflected in the upregulation of zeb1 in stromal cells induced by the positive trophic stimuli of these hormones." (PMID 21324165, 2011). "More importantly, they have also demonstrated that ZEB1 is necessary for tumor-initiating capacity of pancreatic and colorectal cancer cells." (PMID 21643534, 2011). "We found down-regulation of E-cadherin and up-regulation of mesenchymal markers such as vimentin and ZEB1 in tumor tissues derived from PC3 PDGF-D cells compared with PC3 Neo control cells." (PMID 20805998, 2010). "Upon ZEB1 knockdown, there was a strong reduction of lung metastasis after splenic injection of tumor cells in nude mice." (PMID 24281177, 2010). "For carcinomas of colorectal, breast, lung, renal, endometrial and prostate origin, ZEB1 expression has been shown to be restricted to dedifferentiated tumor cells." (PMID 24281177, 2010). "Further investigation of other E-cadherin repressors (e.g. ZEB1) including a larger cohort will help to elucidate the contribution of EMT to tumor progression in OSCC and other cancers." (PMID 20181105, 2010). "With respect to its function in cancer cells, an important question is where ZEB1 is expressed in human tumor tissue samples." (PMID 24281177, 2010). "Targets of these microRNAs were found to be E-cadherin transcriptional repressors ZEB1 and SIP1, factors previously implicated in tumour metastasis." (PMID 21152091, 2010). "The loss of ZEB1 function restores Lgl2 levels and the epithelial phenotypes in tumor cells, which suggests that Lgl2 acts as an effector of ZEB1 in tumor suppression." (PMID 19911055, 2009). "Functionally, miR-150 targets ZEB1, a key EMT driver implicated in stem-like tumor cell features." (PMID 41596525, 2026). "As one of the most important tumor progression regulators, Zinc Finger E-box Binding Homeobox 1 (ZEB1) is a transcription factor that has a key role in epithelial-mesenchymal transition (EMT), which is essential in the metastasis, drug resistance, and plasticity of cancer cells in CRC." (PMID 41899428, 2026). "ZEB1 silences the expression of epithelial markers, including E-cadherin, and it induces the development of mesenchymal properties, such as invasion and metastasis, i.e., tumor aggressiveness." (PMID 41899428, 2026). "The loss of significance of ZEB1 and other EMT-TFs in the combined model likely reflects overlapping prognostic information, as EMT activation may contribute to tumor progression features already captured by pathological staging." (PMID 41481650, 2026). "By triggering EMT, the transcription factor ZEB1 promotes tumor invasion and metastasis." (PMID 40918458, 2025). "In this patient ZEB1 protein abundance in tumor tissue was high in our screen." (PMID 40830586, 2025). "Indeed, we observed a decrease in primary tumor growth and, conversely, an increased collective invasion of E‐cadherin‐, ZEB1‐, and vimentin‐positive tumor budding and metastasis to the lungs." (PMID 40644310, 2025).
tumor (continued). "Conversely, overexpression of HDAC7 reversed the attenuation of tumour growth and metastasis and the suppression of c-Myc and ZEB1 expression mediated by downregulation of DNMT3a, further indicating the existence of positive feedback regulation between DNMT3a and HDAC7 in LUAD." (PMID 39990668, 2025). "Zeb1-positive CAFs, in particular, promote tumor progression through these growth factors." (PMID 40784879, 2025). "ZEB1 is heterogeneously expressed in tumor cells and in cells of the TME27,28,30,32,33." (PMID 40595293, 2025). "Additionally, in breast cancer, excess ROS can inhibit epithelial-mesenchymal transition (EMT) by regulating the miR-200c/ZEB1 axis, thereby suppressing tumor metastasis." (PMID 40424719, 2025). "Interestingly, CRISPR/Cas9-mediated KO of Zeb1 together with forced Snail expression in HMLER cells was accompanied by an arrest in the mixed/hybrid E/M state and an increased inherent tumor initiation capacity, which is a hallmark of CSCs." (PMID 40806166, 2025). "Thus, hypoxia induced tumor derived exosomal ZEB1 was demonstrated to promote immune evasion and escape from innate immune surveillance in cervical squamous carcinoma cells by modifying the activity of the CD47/SIRPα/STAT3 axis." (PMID 39928285, 2025). "For example, M13HS-2 Zeb1-KO tumor hybrids showed significantly higher expression levels of the malignant human mammary stem cell marker aldehyde dehydrogenase 1 (ALDH1) but exhibited decreased colony and mammosphere formation capacities compared with wild-type M13HS-2 tumor hybrids." (PMID 40806166, 2025). "Similarly, in 5-FU-exposed isolated HT-29 cells, all EMT-related genes, including TWIST1, SNAIL1, ZEB1, Vimentin, and N-cadherin, showed upregulation than parental cells, while the tumor and EMT suppressor protein E-cadherin experienced downregulation." (PMID 40251609, 2025). "Therefore, in studying the effects of SB218078 on tumor angiogenesis, we also examined its impact on ZEB1, yielding promising results." (PMID 40160462, 2025). "Moreover, it can induce the epithelial-mesenchymal transition, promoting tumor metastasis by upregulating ZEB1 and MMPs." (PMID 40016703, 2025). "Our previous research also elucidated the role of ZEB1 in tumor angiogenesis." (PMID 40160462, 2025). "Furthermore, OT1-CD8+ T cells showed a dramatic antitumor effect in vivo when ZEB1 was knocked down in tumor tissue, highlighting the key function of ZEB1 in regulating the sensitivity of PC to CAR T cell therapy." (PMID 40924501, 2025). "Statistical analysis confirmed that circ-ZEB1 expression was increased in III–IV stage cancer tissues, suggesting that higher expression of circ-ZEB1 may be linked to tumor invasion." (PMID 39802932, 2025). "To pinpoint the crucial factors mediating the interaction between PC cells and neutrophils, we analyzed intercellular communications involving ligand-receptor pairs and found that the SPP1 (tumor)–CD44 (neutrophil) signal was dramatically inhibited in the ZEB1 KD group." (PMID 40924501, 2025). "Due to the study’s design, which involves obtaining healthy liver tissue from the immediate vicinity of the tumor, the low expression of ZEB1 may be attributable to tumor cells migrating into the surrounding tissue." (PMID 40830586, 2025). "ZEB1 is one of the key TFs that promote cellular plasticity and tumor metastasis in PC." (PMID 40924501, 2025). "Based on these studies, understanding the interaction between MYH11 and ZEB1 and their role in tumor biology may provide insights into new therapeutic targets and prognostic markers." (PMID 40918458, 2025). "Moreover, KN612 treatment reduced the number of Zeb1-positive cells surrounding the primary tumor mass." (PMID 40405188, 2025). "Furthermore, we noticed decreased infiltration of neutrophils in the tumor microenvironment when HDAC1 or ZEB1 was blocked." (PMID 40924501, 2025).
tumor (continued). "Specifically, miR-34a inhibits the expression of epithelial–mesenchymal transition (EMT)-related genes such as SNAIL (Snail Family Transcriptional Repressor) and ZEB1 (Zinc finger E-box-binding homeobox 1), which are critical for the metastatic spread of tumor cells." (PMID 40427514, 2025). "AUF1 further enhances cell invasion and proliferation by concurrently stabilizing the mRNAs associated with epithelial-mesenchymal transition inducer ZEB1 and AKT signaling pathway activator PDK1; its activity can be inhibited by tumor suppressor microRNAs miR-141/146b-5p." (PMID 41019082, 2025). "Nuclear Zeb1 immunoreactivity was observed at the xenoplanted tumor invasion front." (PMID 40396518, 2025). "In patient 2 (primary FL to relapse FL after a 2-year gap), there was a significant increase in Tumor B1 cells (from 2.89% to 74.56%), indicating that TFs enriched in Tumor B1, such as ZEB1, SNAI2, and ID4, may drive FL relapse." (PMID 41238550, 2025). "To elucidate how ZEB1 KD in tumor cells could impair the function of CD8+ T cells through neutrophils, we established a coculture system with these 3 cell types and then collected them for analysis." (PMID 40924501, 2025). "Based on the fact that SB218078 is designed as a competitive binding inhibitor against chk1, we inferred that SB218078 could inhibit tumor angiogenesis by regulating the transcription of ZEB1 and thereby inhibiting the expression of VEGFR2." (PMID 40160462, 2025). "While the exact histone residue responsible for this regulation in neuroendocrine prostate cancer has not been unequivocally mapped, current evidence supports a model in which lactylation at H3K18 or H3K9 promotes ZEB1 expression and facilitates lineage plasticity during tumor progression." (PMID 41583433, 2025). "The ZEB (Zinc finger E-box binding homeobox) family consists of two key members, ZEB1 and ZEB2 which repress the expression of E-cadherin, leading to the loss of epithelial characteristics and promoting tumor invasiveness." (PMID 39615277, 2025). "Furthermore, we are conducting a comparative analysis of total ZEB1 and Drp1 protein and RNA expression levels in donor-matched liver tumor and non-tumor liver tissues obtained from Western Caucasian individuals." (PMID 40830586, 2025). "Our study identifies ZEB1 in TAMs as a facilitator of anti-tumor immunity, suggests a window of opportunity for cytokine-guided CTL tropism and reinforces the importance of onco-immunological context, particularly in the design of macrophage- and/or cytokine-depleting strategies." (PMID 40595293, 2025). "This pathway may play a role in mediating tumor resistance to chemotherapeutic treatments since ZEB1 knockout was shown to increase gemcitabine sensitivity." (PMID 40072059, 2025). "Thus, based on our cell models, it was important to study the contribution of ZEB1 factor to the melanocyte’s differentiation, the spindle cell morphology and their relationship to the invasive type of tumor." (PMID 41226394, 2025). "Particularly in light of the intracellular heterogeneity in ZEB1 expression even within the same cell subtype, it will be relevant to explore differential functions of the potentially selectively targetable ZEB1-high and ZEB1-low cells therein, similar to our recent study in tumor cells." (PMID 40595293, 2025). "Additionally, ZEB1 has also been shown to have pro-tumorigenic effects in other components of the TME by mediating interleukin (IL)-2 suppression in tumor-specific T cells." (PMID 41244268, 2025). "Therefore, the upregulation of ZEB1 during EMT enhances the sensitivity of tumor cells to ferroptosis." (PMID 40709182, 2025).